RNU6-497P (RNA, U6 small nuclear 497, pseudogene)
Gene: Small nuclear RNA gene on chromosome 20 (47,484,278 to 47,484,381, reverse strand). Ensembl gene ENSG00000202186.
Homologues: Orthologues: macaque U6 (99% identical), chimpanzee U6 (98% identical). Paralogues in human: RNU6-1094P (88% identical), RNU6-242P (88% identical), RNU6-637P (88% identical), RNU6-24P (88% identical), RNU6-28P (88% identical), RNU6-43P (88% identical), RNU6-1091P (87% identical), RNU6-1216P (87% identical), RNU6-1274P (87% identical), RNU6-189P (87% identical), RNU6-529P (87% identical), RNU6-727P (87% identical), and 1289 more.